IL13 (interleukin 13)
Diseases named in the same sentence as IL13 in open-access papers (continued):
Sharing a sentence is not in itself a finding about the gene and the disease.
colitis (continued). "Taken together, these observations suggest that IL-13 plays an important role in EC cell biology and 5-HT production and in generation of inflammation in DSS colitis." (PMID 24015275, 2013). "The representative Th2 cytokine IL-13 is expressed abundantly in the inflamed intestinal mucosa and reported to be profoundly involved in development of OXN-induced colitis." (PMID 24348533, 2013). "To evaluate the role of decreased 5-HT production in IL-13−/− mice and its significance in the reduced severity of DSS-colitis in these animals, we treated IL-13−/− mice with 5-HTP, the direct precursor of 5-HT." (PMID 24015275, 2013). "To determine the cellular sources of IL-13 during oxazolone colitis, we isolated LP and MLN cells on day two post-challenge and, using intracellular cytokine staining, examined which cell types expressed IL-13 by flow cytometry." (PMID 22539101, 2012). "Surprisingly, our data show that pretreatment with La-IFN-β exacerbates DSS colitis, with an increase in TNF-α, IFN-γ, IL-17A and IL-13 production by intestinal tissues over the controls." (PMID 21365015, 2011). "Those that were upregulated by 1 log fold or higher include IL-9, IL-13, IL-4, IL-17A, IL-5, IL-24, IFN-γ, IL-10, IL-11, and IL-27, many of which are known cytokines involved in the pathogenesis of colitis." (PMID 21365015, 2011). "In the context of OXA-induced colitis, KGM administration resulted in a marked reduction in the levels of critical inflammatory cytokines, specifically interleukin-4 (IL-4) and interleukin-13 (IL-13)." (PMID 40061034, 2025). "Although IL-13 is important for OXA-induced colitis by using an IL-13 receptor alpha 2-Fc fusion protein, clinical trials targeting IL-13 failed to significantly improve clinical responses." (PMID 36671815, 2023). "CD90-negative and CD90-low CD127+ ILC were a potential source of IL-13, IFNγ and IL-17A at steady state and upon dysbiosis- and dextran sulphate sodium-elicited colitis." (PMID 37114052, 2023). "Among others, IL-4 and IL-13 are key effector cytokines in human UC and DSS-induced murine colitis." (PMID 36558966, 2022). "In this study, we describe and prove the hypothesis that excessive CORT could exacerbate OXA-induced colitis by stimulating ILC2 and that blocking IL-13/STAT6 signaling could reduce CORT-induced exacerbation of colitis." (PMID 36032134, 2022). "Evelyn Saba and colleagues found that ginsenoside Rg3 (20 mg/kg) could decrease the expression of pro-inflammatory mediators and cytokines including NO, IL-1β, IL-5, IL-13, and TNF-α, and levels of NLRP3 inflammasome in DSS-induced colitis mice." (PMID 36160392, 2022). "In accordance, we found that, after induction of colitis by DNBS, the signaling cascade through transcription factor NF-κB activation was markedly increased, as well as the level of pro-inflammatory cytokines such as IL-5, IL-9, and IL-13." (PMID 35893393, 2022). "As for colitis, it has been shown that TRM cells are increased in the gut of patients with IBD and have a pro-inflammatory phenotype that CD69+ T cells expressed higher levels of IFNγ, IL-13, IL-17A, and TNF mRNA than CD69− T cells." (PMID 35844584, 2022). "In support of this, recent studies have shown that IL-13 acts to mediate recovery and repair in the gut following dextran sulphate sodium (DSS)-induced colitis, which is Th1 driven, as disease was improved in both IL-13Rα2 KO mice and in mice treated with a neutralizing IL-13Rα2 antibody." (PMID 34078488, 2021). "Taken together, our data suggests that blocking IL-4/IL-13 signalling specifically on lysozyme M-positive macrophages and neutrophils has no significant influence in the onset of colitis." (PMID 32410852, 2020). "In contrast, but in agreement with increased UC disease severity observed in FliiTg/Tg mice, distal colons of these colitis-induced mice showed an exacerbated immune response with significantly increased expression of Th1 and Th2 cytokines including TNF-α, IFN-γ, IL-5 and IL-13." (PMID 31488864, 2019).
colitis (continued). "This study investigated the contribution of major T cell cytokines and T regulatory cells (Tregs) to inflammation and fibrosis induced in a model of experimental colitis by oral intake of dextran sodium sulphate (DSS) in wild type and IL-13 knock-out C57Bl/6 mice." (PMID 31296924, 2019). "PEG2, rather than IL-4 or IL-13, was found in this study to play a critical role in potentiating the anti-inflammatory M2 phenotype in the early stage of colitis in miR-155−/− mice." (PMID 29774026, 2018). "The level of Th1 cytokine-IFN-γ was significantly higher, but the levels of Th2 cytokine-IL-4, IL-5 or IL-13, and Th17 cytokine-IL-17A were greatly lower in colonic LP of IL-21RKO mice after DSS-induced colitis as compared with those in C57BL/6 mice (**P < 0.01 or ***P < 0.001)." (PMID 27545302, 2016). "Overall, these results suggest that mice deficient in IL-13 have increased susceptibility to acute DSS-induced colitis, ruling out the possibility that the decreased susceptibility to DSS-induced colitis in IL-25−/− mice is due to a lack of IL-13." (PMID 25937893, 2014). "The Th2 cytokines IL-4 and IL-13 were apparently boosted in MLN and spleen lymphocytes of mice treated with T. spiralis AES in this study, but not significantly in treated mouse colons that represents a local response to DSS-induced colitis." (PMID 24788117, 2014). "The increased production of IL-13 and the resulting increase in 5-HT observed in the DSS model of colitis and the role of 5-HT in the other models of colitis previously observed, prompted investigation into the effects of this association in another model of experimental colitis." (PMID 24015275, 2013). "To investigate whether decreased 5-HT production and reduced severity of colitis observed in IL-13−/− mice was restricted to the DSS model; we induced DNBS colitis in IL-13−/− mice." (PMID 24015275, 2013). "Similarly, when IL-13 downstream effector functions are blocked, via the elimination of NKT cells or by using an IL-13 receptor α2-fusion protein, the development of colitis is prevented, whereas antibodies against IL-12 severely aggravate the disease." (PMID 22539101, 2012). "In our gene expression data, IL-13 is upregulated 2.68 log fold in colitic mice pretreated with La-IFN-β, which again supports our conclusion that La-IFN-β exacerbates colitis and that this may be a result of the inability of IFN-β to signal." (PMID 21365015, 2011). "Moreover, colitis mice treated with 50 μg TA exhibited significant increases in IL-13 and IL-5Rα levels, which likely contribute to the exacerbation of colitis symptoms rather than promoting resolution." (PMID 40333150, 2025). "A similar trend was observed in our previous studies, which revealed that mice with colitis subjected to voluntary moderate training or forced moderate training had significantly elevated adiponectin plasma levels, while plasma concentrations of leptin, TNF-α, IL-6 and IL-13 were markedly reduced." (PMID 33557311, 2021). "Macroscopic and microscopic colitis in sedentary SD mice was accompanied by a significant fall in CBF, some increase in colonic tissue weight and a significant increase in the plasma levels of tumour necrosis factor-alpha (TNF-α), IL-6, monocyte chemotactic protein 1 (MCP-1) and IL-13 (p < 0.05)." (PMID 28425943, 2017). "Nuocytes have been described recently as a new innate cell type that is responsive to IL-25 and is the main producer of IL-13 in the gut during helminth parasite infection and here we found for the first time the presence of this new type-2 innate lymphoid cell (ILC) during inflammation in colitis." (PMID 22539101, 2012). "Therefore, because IL-25 is known for driving IL-13 production by IL17BR+ cells and for inducing type-2 inflammation in the lung and gut, we hypothesized that IL-25 might have a pro-inflammatory role in the type-2 model of colitis." (PMID 22539101, 2012).
colitis (continued). "We next assessed the cytokine production in ILC2s and observed that production of IL-5, but not IL-13, was significantly reduced in DSS-induced colitis when stimulated by PMA plus ionomycin." (PMID 36268010, 2022). "Last, we could show that in absence of IL-13, DSS colitis with intestinal remodeling and fibrosis could still be induced in a similar manner as in WT animals." (PMID 31296924, 2019).
psoriasis (109 papers, 2010 to 2026). An autoimmune condition characterized by red, well-delineated plaques with silvery scales that are usually on the extensor surfaces and scalp. "Supporting this, genetic studies have demonstrated that genetically mimicked IL-13 inhibition is associated with an increased risk of psoriasis and psoriatic disease." (PMID 41542312, 2026). "This represents the first reported case of psoriasis associated with lebrikizumab in a patient with AD and adds to the growing body of evidence implicating IL-13 inhibition as a potential contributor to psoriatic disease pathogenesis." (PMID 41542312, 2026). "Research on psoriasis susceptibility genes found that there is a 1.18-fold increase in loci related to IL-4/IL-13 signaling." (PMID 39859462, 2025). "AD is classically associated with dysregulation of the Th2 subset (IL-4, IL-5, IL-13, and IL-31), whereas the Th17 subset (IL-17, IL-21, and IL-22) has been implicated in the pathogenesis of psoriasis." (PMID 40535962, 2025). "Another common genomic region is located on chromosome 5q31.1-q33.1, where IL-13 has been linked to both AD and psoriasis." (PMID 39859462, 2025). "On the other hand, although dupilumab, a dual inhibitor of IL-4 and IL-13 signaling, has been used successfully in BP, it is generally known to cause psoriasis." (PMID 38545121, 2024). "The recently identified Th22 effector T cell subset, characterized by IL-22 and IL-13 production, has also been implicated in psoriasis." (PMID 37662940, 2023). "A study in Japan found a marginal association between AD and two psoriasis susceptibility SNPs, IL-13(rs1295685) and ZMIZ1(rs1250546)." (PMID 36314037, 2022). "Examples are accumulation of granulocytes stimulated by IL-8, IL-17, IL-9 and IL-13; epidermal hyperplasia and psoriasis-like skin lesions due to IL-22; and fever and weight loss in response to IL-6 and IFN-γ." (PMID 34503066, 2021). "Exceptions included genes located at the MHC locus showing a potential increase in risk of ulcerative colitis and multiple sclerosis, and at the IL5/IL13 locus showing a potential increase in risk of psoriasis." (PMID 34103634, 2021). "SLC22A5 has previously been reported to be associated with IBD25, whereas previous psoriasis reports relating to chromosome 5q31 have focused on variants mapping to the IL13 gene." (PMID 25651891, 2015). "Our results showed an association between another SNP in IL13 (rs1800925) and type I psoriasis (p = 0.034)." (PMID 26613086, 2015). "Compared with monoculture, psoriasis-derived mesenchymal stromal cells (PsO-MSCs) co-cultured with healthy donor MSCs (H-MSCs) secreted substantially lower levels of hallmark psoriatic pro-inflammatory cytokines (IL-6, IL-12, IL-13, IL-17A, TNF, and G-CSF)." (PMID 41226338, 2025). "In addition, IL-13 associated with chromosomal region 5q31.1-q33.1 plays a role in both psoriasis and AD." (PMID 41149056, 2025). "Interestingly, the two diseases had another common region on the genome, chromosome 5Q31.1-Q33.1, where IL-13 was associated with both AD and psoriasis." (PMID 36314037, 2022). "IL13 polymorphisms were proposed as PsA markers among psoriasis patients in the earlier reports but this gene was later identified as a risk region for cutaneous-only psoriasis as well albeit with a weaker association in a large GWAS meta-analysis." (PMID 33581710, 2021). "IL-13 polymorphisms, such as rs1800925, rs20541 (G/A; Arg130Gln; exon 4), and rs848 (C/A; 3′ untranslated region), have also been studied in the context of PsA and psoriasis." (PMID 34831223, 2021). "Interestingly, associations of regions encoding Th2-related genes, particularly IL-4, IL-5, and IL-13, with the region of chromosome 5q31 containing multiple cytokine genes have also been found in patients with psoriasis." (PMID 29292715, 2017). "However subsequent large psoriasis studies, including subtype analysis, have all reported robust association to IL13 (refs 19, 20)." (PMID 25651891, 2015).
psoriasis (continued). "Both SNPs in IL13 have been associated with predisposition to psoriasis." (PMID 26613086, 2015). "In psoriasis an association with three variants of the IL-13 gene was observed: rs1800925, rs20541, and rs848 (This cytokine, such as IL-4 and IL-10, is secreted by Th2 lymphocytes and seems to be important in the innate and adaptive immune response dysregulation that leads to psoriasis)." (PMID 23971052, 2013). "Moreover, the CCG haplotype of rs1800925-rs20541-rs848 in IL13 was associated with susceptibility to psoriasis in a study performed in 1446 cases and 1432 controls." (PMID 24069534, 2013). "Since IL-4 and IL-13 are key mediators of Th2-mediated inflammation, their blockade by dupilumab may induce a shift from Th2-mediated inflammation to Th1/Th17 subsets, causing psoriasis." (PMID 39931435, 2024). "Moreover, decreased expression of filaggrin in the lesional skin of psoriasis due to secreted cytokines including IL-4, IL-13, IL-17, and TNF-α might increase the risk of skin cancer by increasing UV sensitivity of patients with psoriasis." (PMID 32987907, 2020). "The main cytokines involved in the pathogenesis of psoriasis are certainly TNFα, IL-12, IL-17, and IL-23, whereas in the pathogenesis of AD, IL-4, IL-13, and IL-31." (PMID 41481132, 2026). "It connects microbiome composition and function with systemic inflammation and cutaneous pathology, shaping disease-specific mechanisms such as Th2/IL-4/IL-13-mediated barrier dysfunction in AD and Th17/IL-23/IL-17-driven hyperproliferation in psoriasis." (PMID 41972685, 2026). "HSO were also treated with Th1 (TNF-α + IL-17) and Th2 (IL-4 + IL-13) cocktails inducing pro-psoriasis and pro-AD HSO changes, respectively." (PMID 41993536, 2026). "Conversely, in AD, the emergence of psoriasis or psoriasiform eruptions has been reported, most notably with dupilumab, an IL-4/IL-13 inhibitor, and more recently with tralokinumab, a selective IL-13 inhibitor." (PMID 41542312, 2026). "This case contributes to the current knowledge base for JAK inhibitors and suggests that patients who develop psoriasis on IL-4/IL-13 biologic therapy for AD can be treated safely and effectively with JAK inhibitors." (PMID 39906475, 2025). "This review clearly supports the effectiveness of targeting the IL - 4/IL-13 pathway (e.g., dupilumab) and provides theoretical support for understanding the role of innate immune cells in chronic skin inflammation, including psoriasis." (PMID 41209017, 2025). "They observed overlapping patterns of inflammation and keratinocyte activity between Blaschko linear psoriasis and psoriasis vulgaris but also detected notable differences, particularly in pathways related to IL-4, IL-13, and IL-36 signaling." (PMID 40539143, 2025). "Psoriasis primarily involves the TNF-α and the IL23-Th17-IL17 pathway, while AD is associated with a Th2 response driven by IL-4 and IL-13." (PMID 39859462, 2025). "The dual role of IL-13 in psoriasis exists in the lesion sites of psoriasis, where it can jointly alleviate the inflammatory response." (PMID 40507886, 2025). "skin dataset, we detected a positive enrichment of IL‐4 + IL‐13 signatures in AD and psoriasis compared to healthy controls." (PMID 40926620, 2025). "Monoclonal antibodies targeting the interleukin (IL)-4/IL-13 and the IL-17/IL-23 axes are available for the treatment of AD and psoriasis, respectively." (PMID 39161766, 2024). "In AD, the predominant cytokines are IL-4, IL-5, and IL-13, and the pathogenesis differs from that of psoriasis." (PMID 39519167, 2024). "We determined susceptibility of KC to VV and HSV-1 infection after exposure to representative cytokines prevalent in diverse inflammatory cutaneous diseases: IFNγ (lupus/AD; type 1), IL-4 and IL-13 (AD; type 2), IL-22 and IL-17A (psoriasis/AD, type 3)." (PMID 37298195, 2023). "The anti-inflammatory genetic mediators associated with psoriasis are IL1RN, IL4, IL10, IL13, and IL19." (PMID 37569685, 2023).